VIM (vimentin)
Diseases named in the same sentence as VIM in open-access papers (continued):
Sharing a sentence is not in itself a finding about the gene and the disease.
tumor (continued). "In addition, the E-cadherin protein level was increased, whereas the MMP9, Twist, and Vimentin protein levels were decreased in the UA-treated xenograft tumor tissues as compared with those in the control tumor tissues." (PMID 31547587, 2019). "Immunohistochemistry studies showed diffuse positivity of tumor cells with Vimentin, EMA, and S100." (PMID 31754365, 2019). "In GBM we observed a similar, less prominent, pattern of MES-like αDG+/vimentin+ tumour tissue often detected in large tumour sections, indicating that GBM may also undergo a similar EMT-like process." (PMID 31463571, 2019). "Furthermore, near tumor invasive front, high level of CD163 was associated with less E-cadherin and more Vimentin, an indication of EMT." (PMID 30927925, 2019). "Indeed, withaferin-A, a naturally derived bioactive compound that targets vimentin and induces vimentin cleavage, suppressed tumor growth and metastasis in various mouse models." (PMID 31126068, 2019). "Interestingly, weaker staining of SMG1 was observed in the edges of the tumor masses than in the centers, in contrast with the staining of Ki-67, Snail and Vimentin, which was stronger in the tumor edges than in the centers." (PMID 31659158, 2019). "Moreover, there was a higher PD–L1 level of expression when ≥25% tumor cells were positive for vimentin (14 ± 25 vs. 43 ± 38 PD–L1 positive cells; p < 0.0001)." (PMID 31546725, 2019). "Vimentin (increased for the group >200 colonies) is considered a negative prognostic factor in AML, whereas SMG1 (decreased for the group >200 colonies) is a potential tumor suppressor in hypoxic tumors and associated with regulation of AML cell proliferation." (PMID 30634713, 2019). "Furthermore, tumor cells showed high expression of Vimentin on the cell surface as measured by Western blot assay, while the expression of E-Cadherin decreased markedly." (PMID 31552179, 2019). "Epithelial-to-mesenchymal transition (EMT), which indicates the conversion of epithelial cells to migratory mesenchymal cells, has been shown by intermediate keratin/vimentin expression ratios, and we sorted stromal and tumor cells with vimentin antibody and keratin antibody." (PMID 29525983, 2018). "Similar patterns of actin and vimentin rearrangement, accompanied by a decrease of the migratory and invasive behavior of tumor cells have been described in several other studies evaluating anti-metastatic effect of various compounds with potential anticancer activity." (PMID 29495431, 2018). "All tumour cells, including vimentin-positive ones, were positive for cytokeratin." (PMID 29976164, 2018). "In addition, the expression level of vimentin in the metastatic tumour nodules that of the sh-CCAL group was reduced as detected by IHC." (PMID 30250169, 2018). "Although vimentin overexpression in cancer cells has been reported to be closely correlated with accelerated tumor growth, migration, and invasion, specific regulation of the phosphorylation status of vimentin during the development of cancer remains poorly understood." (PMID 29724197, 2018). "They observed that targeting vimentin at the cell surface of glioblastoma stem using a monoclonal antibody, resulted in apoptosis and suppressed proliferation of cells ex vivo, as well as reduced tumour size and increased survival in vivo." (PMID 30248895, 2018). "However, a comment is needed on vimentin: in general, expression was restricted to few cases (19 metastasis, only 3 corresponding primary tumours), which makes statistical significance questionable." (PMID 29976164, 2018). "Our finding of tumour cells coexpressing vimentin and cytokeratin at the bulk border and of reduced expression of E-Cad in these bulks (staining intensity equivalent to decreased receptor density) probably results in more freedom of movement while still keeping the cell together." (PMID 29976164, 2018).
tumor (continued). "In addition, all specimens were also stained with the IHC antibodies specific for MPM, such as calretinin, cytokeratin 5/6, and vimentin, to confirm that tumor antigenicity was completely maintained." (PMID 29755688, 2018). "Furthermore, the tumor sections were stained for E-cadherin, FN1, ZEB1 and vimentin expression to quantitatively evaluate the EMT associated marker." (PMID 30098599, 2018). "Since vimentin-positive tumor cells are rather difficult to distinguish from stromal cells by IHC staining, especially in the solid type of ACCs, we performed co-immunofluorescence (co-IF) staining using an anti-vimentin antibody together with an anti-pan-cytokeratin antibody." (PMID 29596469, 2018). "The IHC staining to human vimentin on lung section showed the presence of tumor foci in the lungs, quantification of the lung areas affected by the metastases showed MS275 reduced lung metastases by 2 fold compared to control (1.9% ± 0.9% for MS275 vs. 3.8% ± 1.5% for control)." (PMID 30547810, 2018). "As compared to CD133− patients, tumor cells in CD133+ patients demonstrated high levels of TGF-β/p-Smad2 as well as EMT-like alteration, characterized by loss of E-Cadherin and expression of Vimentin and S100A4." (PMID 29510695, 2018). "In contrast to the negativity of vimentin staining in lung tissue, the strong vimentin staining in tumor tissue areas has confirmed that these formed tumor foci were derived from metastasis of MDA-MB-468, a TNBC line expressing the high levels of vimentin according to the immunofluorescence study." (PMID 29350614, 2018). "In addition, the compound Arylquin 1 (a 3-arylquinoline derivate) has been shown to specifically bind to vimentin, resulting in tumour cell apoptosis via a secretion-dependent mechanism." (PMID 30248895, 2018). "Resveratrol promotes cell-cell junction, apoptosis and thus blocks EMT, which is consistent with the results from our laboratory that resveratrol induced an epithelial conversion in CRC cells in tumor microenvironment with decreasing of vimentin and slug and increasing of E-cadherin." (PMID 30002278, 2018). "Similarly, expression of the mesenchymal marker Vimentin was increased and localized exclusively to the tumor stroma." (PMID 30135483, 2018). "Tumor metastasis was examined by vimentin staining at lung and liver tissue sections." (PMID 29416640, 2018). "In ovarian cancer cell lines, knock down of Rac1 expression decreased fibronectin production, reversed EMT as measured by increased E-cadherin and decreased vimentin expression, inhibited tumor cell migration and invasion and reduced tumor growth in a xenograft model." (PMID 30261690, 2018). "In addition, in the xenograft environment, as in the primary patient tumor, we observed that some tumor cells lost keratin‐8 expression, while maintaining expression of vimentin." (PMID 29171037, 2018). "Pulmonary metastatic colonisation in mice that had been given EO771.LMB cells via the tail‐vein was assessed by qPCR on DNA extracted from the lungs of the mice [determined by the level of mCherry DNA (present only in the tumour cells) relative to that of vimentin DNA (present in all cells)]." (PMID 30062795, 2018). "Immunohistochemically, tumor cells were stained by vimentin and CD34." (PMID 30473900, 2018). "Thus, miR-22 is presented as a crucial tumor suppressor that controls MAPK1/Slug/vimentin feedback loop and represses Snail expression in BCa cells." (PMID 29434190, 2018). "In total, 26 out of 31 SOX2negtive tumors showed high expression of vimentin in tumor cells." (PMID 29596469, 2018). "Moreover, we found that tumor cells expressed reduced E-cadherin, increased N-cadherin, vimentin, snail and slug after treatment of 14,15-EET, while 14,15-EEZE reversed 14, 15-EET-induced EMT." (PMID 29426357, 2018). "Moreover, single administration of eribulin before the initiation of paclitaxel treatment decreased vimentin expression and reduced the average tumor volume in a mouse xenograft model." (PMID 29796167, 2018).
tumor (continued). "The rfhSP-D treatment of these cell lines for up to 24 h prevented their morphological alterations associated with EMT, reduced tumor cell invasion in the matrigel, downregulated TGF-β production, and downregulated key mesenchymal gene expression, such as Vimentin, Zeb1, and Snail." (PMID 30158928, 2018). "In the tumor, vimentin expression was focal/patchy but it was expressed throughout the NUCOLL43 cells, again consistent with the cells being derived from a clonal sideline of the original tumor that was vimentin‐positive and with chromosome 5q and 7p copy number changes." (PMID 30109783, 2018). "Many studies have shown that down-regulation of Vimentin could significantly inhibit tumor cell invasion and metastasis." (PMID 30249755, 2018). "As this only happened in a minority of tumours, another mechanism such as fascin might replace vimentin in this function, which fits nicely with our results." (PMID 29976164, 2018). "TGF-β1 has been recognized to function as a tumor promoter by inducing EMT, which features the loss of epithelial phenotypes (e.g. E-cadherin) and the acquisition of mesenchymal phenotypes (e.g. N-cadherin and Vimentin)." (PMID 29568359, 2018). "Similarly, transfer of δD910A/D910A macrophages either into NSG mice bearing MDA-MB-231 tumours or into mice with experimental lung metastasis led to reduced expression of vimentin in the lungs reflecting decreased invasion of cancer cells." (PMID 29880805, 2018). "However, vimentin+ tumor cells were morphologically distinguishable from infiltrating, vimentin-expressing monocytes/macrophages." (PMID 30275505, 2018). "Furthermore, to investigate the induction of MET in cancer cells after a single administration of eribulin, we obtained tumor specimens from the xenografts on day 7 and examined the expression of E-cadherin and vimentin by immunohistochemical analysis." (PMID 29796167, 2018). "Vimentin positive expression was chiefly observed in the cytoplasm of spindle tumor cells." (PMID 29609569, 2018). "Furthermore, the tumor cells exhibited robust upregulation of various mesenchymal markers such as vimentin and N-cadherin when stimulated with supernatants from wild-type or Atg5flox/flox TAM." (PMID 28686632, 2017). "Interestingly, expression levels of ACTA2, S100A10 and VIM were positively and significantly correlated to tumor size, suggesting a relationship between NC derived stromal component and tumor growth." (PMID 29163787, 2017). "Furthermore, the level of SOX9 as well as CSC marker CD44 and mesenchymal marker vimentin in tumor xenografts was dramatically diminished by the treatment." (PMID 29237490, 2017). "In addition, staining for ASMA in combination with vimentin was used to define transformed tumour cells as a sign of epithelial to mesenchymal transition (EMT) since ASMA is not expressed in 3D monocultures of cancer cells." (PMID 28592821, 2017). "In addition, the expression levels of 4 EMT-markers (E-cadherin, N-cadherin, cytokeratin 19 and vimentin) were evaluated in human OC ascites- and tumor-primary cultures." (PMID 28934230, 2017). "Again in this study the tumour areas were scaled and compared with vimentin and DAPK1 serum levels." (PMID 28616237, 2017). "WFA induces marked apoptosis and vimentin cleavage in vimentin‐expressing tumor cells." (PMID 28556516, 2017). "Activation of both Stat1 and Stat3 signalling pathways in tumour cells by mMDSCs may account for the induction of EMT/CSC phenotype as assessed by strong upregulation of EMT-related genes such as Vimentin, CK14 and Twist." (PMID 28382931, 2017). "However, tumours derived from CSC-like cells uniformly stained for vimentin, indicative of an only partial reverse EMT process during tumour development in vivo." (PMID 28356569, 2017).
tumor (continued). "We demonstrated here that the hTERT−/− cells might induce a pattern of up-regulated epithelial protein (E-cadherin), while down-regulating mesenchymal-like proteins (N-cadherin and Vimentin), which results in tumor metastasis." (PMID 29156735, 2017). "Elevated serum vimentin concentration may be an indication of tumour promotion and aggression at the molecular level." (PMID 28616237, 2017). "Vimentin’s elevated levels in serum may provide a link to the remote molecular events leading to tumour aggression." (PMID 28616237, 2017). "This change was further evidenced by the disappearance of the mesenchymal character of this tumor, a characteristic observed previously, revealed by a dramatic decrease in the expression of vimentin in all parts of the tumor tissue, in parallel with a decrease in cell density." (PMID 28915695, 2017). "Indeed, in our models, the cross-talk between tumour (human) and microenvironmental (murine) cells seemed to produce a selective pressure that advantaged solid patterns, vimentin expression and eventually complete EMT." (PMID 28751748, 2017). "During EMT, tumor cells gradually lose the epithelial markers (E-cadherin, tight junction protein-1, laminin and cytokeratin) and obtain the expression of mesenchymal markers (N-cadherin, Vimentin and α–SMA)." (PMID 28938653, 2017). "These cells formed tumours with vimentin-positive cells predominantly located along the periphery." (PMID 28094783, 2017). "This pathway stimulates the expressions of the matrix metalloproteinase (MMP) gene, which is required for the induction of cell motility via the degradation of the extracellular matrix, and vimentin gene, which is an important protein in deformation and movement of tumor cells." (PMID 28402270, 2017). "Ki-67, VEGF and Vimentin were well-known markers in relation to tumor growth and metastasis." (PMID 28498813, 2017). "Interestingly, MTE alone also increased E-cadherin levels while suppressing vimentin expression in tumor tissues." (PMID 28915640, 2017). "HIF-1α-positive cells (black arrow) were distributed along the tumor (T)-necrosis (N) border only, corresponding to the region containing the vimentin-positive cells (black arrow), as also seen in islands of tissue surrounding vessels within the necrotic region." (PMID 28750639, 2017). "In addition to the epithelial CSC-enriched spheroid culture (LT22s), we also isolated mesenchymal-like cells of the same tumor, with a high Vimentin expression and a prominent mesenchymal phenotype." (PMID 28855609, 2017). "Vimentin expression has recently gained importance from the point of view of identifying the mesenchymal origin of a cell, as a prognostic marker to predict the biology of the tumor and to detect micro-metastasis." (PMID 28225793, 2017). "Recent observations indicate that vimentin is not only a passive marker for carcinoma, but may also induce tumor cell invasion." (PMID 28117759, 2017). "Moreover, paclitaxel- and gemcitabine-resistant epithelial tumor cells often exhibit increased vimentin expression." (PMID 28475592, 2017). "The combination of EGCG and cisplatin markedly down-regulate the expression of NF-κB p65, Bmi-1, Twist1, and vimentin and up-regulates E-cadherin in human nasopharyngeal CNE2-SCs from the tumor nodules of nude mice, which is associated with the inhibition of tumorigenesis." (PMID 28942499, 2017). "Additionally, our results showed that the metastatic tumor cells in the cervical LNs positively expressed vimentin, ALDH1, and PDK1, suggesting they were endowed with EMT and CSC-like phenotypes." (PMID 27926487, 2017). "A tumour evolution was strongly suggested by LT63, LT220 and LT268 behaviour in mouse, indeed in these models an epithelial to mesenchimal transition (EMT) was appreciable, with loss of TTF-1, acquisition of vimentin and Ki67 expression." (PMID 28751748, 2017).
tumor (continued). "However, increased cytosolic Vimentin expression in tumour cells was observed in 68.9% (82/119) of NPC samples (p < 0.001), especially in the spindle-shaped tumour cells." (PMID 28198387, 2017). "Studies assessing the EMT profile in 20 ascites- and 6 tumor-primary cultures derived from patients diagnosed with advanced-stage high-grade serous OC, showed the expression of E- and N-cadherin, cytokeratin 19 and vimentin mRNA in all samples." (PMID 28934230, 2017). "A notable reduction in CD133, but not CK7 and Vimentin, expression was observed in G6pd knocked-down Ymac-1 tumor, which further supported the notion that G6pd is associated with CSC-like characteristics." (PMID 28596515, 2017). "Furthermore, mMDSCs were detected in situ at the invasive edge of the tumours where strong vimentin expression was observed." (PMID 28382931, 2017). "The translation of both vimentin and Snail1 mRNAs, along with a number of other pro-invasion messenger RNAs, is controlled by mTORC1, likely explaining their inhibition and restoration of E-cadherin in 64B-treated tumor cells." (PMID 29245898, 2017). "In contrast, STA-8666 did not affect tumor features, such as degree of vimentin staining, associated with epithelial-mesenchymal transition (EMT), or downregulate tumor expression of HSP90." (PMID 28453558, 2017). "Among them, vimentin and ezrin, which are known to be involved in the regulation of metastasis, were down-regulated under the treatment of tachyplesin I, suggesting that cytoskeleton are influenced by tachyplesin I, thus contributes to its anti-tumor activity." (PMID 28106765, 2017). "During microdissection, we collected the stroma (vimentin-positive) immediately associated with tumor epithelial cells rather than stromal tissue distal to the tumor, and excluded lymphocytes and obvious vascular structures." (PMID 28102840, 2017). "Additionally, we performed IHC for the expression of K5 and differentiation specific marker K1, on the same tumor samples whose vimentin and K14 expression was determined previously." (PMID 28225793, 2017). "The following effects were observed with HK2 knockdown: inhibition of cell migration and invasion; reduced SOD2 activity and intracellular H2O2 levels; suppression of pERK1/2, Slug and Vimentin expression; and inhibition of tumour growth and lung metastasis in vivo." (PMID 27926482, 2017). "In addition to cells in the tumor core, invasive tumor cells (single cells, micro-satellites, and perivascular spread) were also strongly (++++) VIM positive." (PMID 29152094, 2017). "In order to translate these in vitro findings to the bedside, E-cadherin, N-cadherin, cytokeratin 19 and vimentin mRNA expression levels were evaluated in 6 tumor- and 20 ascites-primary cultures derived from patients diagnosed with advanced-stage high-grade serous OC." (PMID 28934230, 2017). "Aberrant expression of E-cadherin, Vimentin and Snail is associated with EMT and tumor metastasis." (PMID 28327189, 2017). "Thus, this study depicts the modulatory role of vimentin to fine tune the differentiation switch to favor tumor progression." (PMID 28225793, 2017). "p62 functions as a tumour metastasis promoter through its interaction with vimentin." (PMID 28968743, 2017). "On immunohistochemical evaluation, the tumor cells were positive for Vimentin, CD68, CD34, Nestin, GFAP, Desmin, SMA, AE1/AE3, and S-100 protein, but were negative for NSE, Synuclein, NeuN, EMA, pituitary hormones (LH, FSH, ACTH, TSH, growth hormone, and prolactin), synaptophysin and chromogranin." (PMID 28121922, 2017). "Immunostaining with epithelioid MPNST marker, S100β, showed strong expression in spindle-shaped tumor cells (2D’) while the mesenchymal marker, Vimentin, also showed extensive staining in tumor tissues of cdkn2a/b TALEN mRNA injected tp53e7/e7 mutant zebrafish (2E’)." (PMID 28903419, 2017).